TNF (tumor necrosis factor)
Diseases named in the same sentence as TNF in open-access papers (continued):
Sharing a sentence is not in itself a finding about the gene and the disease.
tumor (continued). "When inflammatory substances like interferon-gamma and lipopolysaccharide excite monocytes, they activate M1 macrophages, which can emit inflammatory factors like IL-6 and tumor necrosis factor-alpha and phagocytize invading infections and tumor cells." (PMID 36589842, 2022). "TNF regulates different signaling pathways in the tumor microenvironment through TNFR2 and participates in the occurrence and growth of tumors." (PMID 35494080, 2022). "Imprime’s establishment of this immuno-supportive microenvironment also allowed increased trafficking of activated cytotoxic T cells (CD8+/Ki67+/GrzB+) with effector phenotype (IFN-γ+/IL-2+/TNF-α+) into the tumor." (PMID 35692755, 2022). "This also suggests that the CNGRCG peptide (NGR) and the CD13 receptor represent an efficient ligand–receptor system for delivering TNF to the tumor vasculature." (PMID 35890309, 2022). "TNFα and IL-1β from tumor cells enable activation of CAFs to produce thymic stromal lymphopoietin (TSLP), which promotes Th2 polarization via DC conditioning." (PMID 36230914, 2022). "It is worth mentioning that the impaired expression of CRY1 was associated with elevated levels of pro-inflammatory cytokines, such as tumor necrosis factor alpha (TNF-α), which can mediate pro-survival or pro-death signals after tumor target recognition." (PMID 35897788, 2022). "Once in the site, MDSCs stimulate the migration of tumor cells by secreting TNFα, CXCL2, TGFβ, IL-6 and CCL2." (PMID 35158779, 2022). "In lung cancer, tumor-associate macrophage (TAM) containing iron has been demonstrated to increase ROS level and secrets proinflammatory cytokines (e.g., TNFα, IL-6) to kill tumor cells." (PMID 35401569, 2022). "TANs isolated from early tumors produced higher levels of NO, H2O2, and TNF-α and demonstrated greater cytotoxicity against tumor cells in comparison with TANs isolated from late-stage tumors." (PMID 36555469, 2022). "To gain a better understanding of the role of pro-inflammatory cytokines in PCa progression, we analyzed messenger RNA (mRNA) levels of IL-6 and TNFα from 49 somatic tumor tissue samples (see “Methods” section)." (PMID 36371231, 2022). "As immune cells are pivotal in the antitumor response, CTLs directly target tumor cells for lysis, promoting selective apoptosis of the target cells via perforin/granzyme and Fas/tumor necrosis factor-mediated mechanisms." (PMID 35402219, 2022). "TNF-α can exert both tumour-inhibitory or tumour-promoting effects by inducing apoptosis or necroptosis, cell growth, cellular invasion or propagation of cancer cells." (PMID 36347875, 2022). "Another subsequent study demonstrated that Defensin can suppress tumor progression by targeting phosphatidyl serine on tumor cell membranes and inducing cell death cooperating with tumor necrosis factor in Drosophila imaginal discs." (PMID 36226812, 2022). "Previous studies have shown that CREB1 regulates the expression of some tumor-related genes, such as tumor necrosis factor-α (TNF-α), c-fos, and Bcl-." (PMID 36313570, 2022). "IL-18 induced increased expansion of Vδ2 T cells stimulated by ZOL and IL-2, and expanded cells displayed an effector memory phenotype, with high levels of production of IFN-γ, TNF-α and strong cytotoxicity against tumor cells like mesothelioma cells." (PMID 36429001, 2022). "An important role of CD8+ T cells is associated both with the secretion of effector cytokines (IFNγ, TNFα), which are involved in the priming and differentiation of cytotoxic cells, and in the direct destruction of infected and tumor cells." (PMID 36560509, 2022). "As described in section Antitumor Effects of Plasmatocytes, tumor apoptosis is also induced by TNF secreted by immune cells." (PMID 35911716, 2022). "Treating tumor cells (such as mouse fibroblast L929) with actinomycin D, mitomycin C, and cycloheximide can obviously increase the killing activity of TNF-α on tumor cells." (PMID 36035842, 2022).
tumor (continued). "Significantly lower percentages of CD3 + T cells expressing the inflammatory cytokines IFNγ and TNFα were detected in S2 and S3 tumours than S1 tumours." (PMID 35301339, 2022). "The effective anti‐tumor immune response of 5-FU chemo-immunotherapy was dependent on CD8+ T cells but was unaffected when TNFα or IL-1β cytokine signaling pathways were blocked." (PMID 35634282, 2022). "TNF-α is another anti-tumor mediator uniquely stored in MC granules and critical for apoptosis of tumor cells following FcεRI activation." (PMID 35740607, 2022). "TNF inhibitors were found to suppress tumor progression by disrupting TNF-α-related tumor-promoting inflammatory signaling in vitro and in vivo." (PMID 35945635, 2022). "CBD attenuates chronic inflammation by completely inhibiting the production of inflammatory cytokines by the tumor microenvironment, including IL-1β, IL-6, interferon-β (IFN-β), and TNF-α, all implicated in initiation and progression of several cancers." (PMID 35456540, 2022). "TNF-α is largely produced by macrophages in inflammatory tissues and contributes to tumor growth, angiogenesis, and wound healing." (PMID 36552229, 2022). "TNF-α can act as an endogenous tumor promoter and participate in promoting and developing human cancers." (PMID 35910071, 2022). "According to the qRT-PCR results, expression levels of NRP1, IGF2R, SERPINA3 and TNF were significantly upregulated in the comparison between in situ tumor samples and normal tissues in our clinical center." (PMID 36406134, 2022). "We observed significant correlation between margin periostin and VEGF-A, IFN-γ, IL-17 and TNFα in tumor and margin specimens." (PMID 35056404, 2022). "M1-like TAMs secreting pro-inflammatory cytokines such as TNF-α, IL-1, IL-6, IL-12 and IL-23 have anticancer effects, while M2-like TAMs contribute to tumor progression." (PMID 36361831, 2022). "For this, we injected tumour‐bearing mice with 5 × 1010 TU/mouse, as the dose we have used previously for phage‐based vectors, then applied RT‐qPCR to identify the expression of TNFα mRNA transcripts in the tumour and key internal organs." (PMID 35758207, 2022). "In this review, we summarize the roles played by TNF-α in the recruitment, immunosuppressive functions, and chemotaxis of MDSCs, and discuss the potential therapeutic effects of TNF-α upon these cells in tumor growth and some inflammatory disorders." (PMID 36358977, 2022). "Cancer-related inflammation, of which TNF is a major mediator, promotes tumor development and progression." (PMID 35844550, 2022). "N2 TANs can promote angiogenesis and tumor cell proliferation, and secrete tumor necrosis factor TNFα, epidermal growth factor to play a tumor-promoting role." (PMID 35965533, 2022). "IL-6 collectively regulates the tumor proliferation target genes as inflammatory cytokines as TNF-α, and several angiogenic growth factors as VEGF." (PMID 35269343, 2022). "TAMs regulate tumor growth, angiogenesis, metastasis, and drug resistance by producing cytokines such as tumor necrosis factor-alpha (TNF-α), interleukin (IL)-6 and IL-1β, and chemokines such as CXC chemokine ligand 1 (CXCL1) and CXCL2." (PMID 36552865, 2022). "CD4+ Th cells not only activate CD8+ CTLs by releasing several cytokines and enhancing the immune efficacies of CTLs but also produce chemokines, IFNs, and TNF, which directly act on the tumor cells." (PMID 35909469, 2022). "TNF therapy induces tumor regression in rodent models, but in humans it results in hypotension and other dose-limiting toxicities, thus preventing its effective use as a systemic anti-cancer therapy." (PMID 36551505, 2022). "We found that N-glycan biosynthesis pathway was activated in high-grade tumor, but TNF-related pathway was activated in cystitis glandularis." (PMID 35265520, 2022).
tumor (continued). "Firstly, we detected several inflammation factors, such as LPS, TNFα, IL-1β and IL-6, in the sera of WT and Hectd3−/− mice burdening primary tumor (0 h) or surgically removed primary tumor 6 h or 12 h later." (PMID 35918322, 2022). "TNF-α upregulation of the NF-κB pathway is a major regulatory step for inflammation, including in the tumor microenvironment." (PMID 35440077, 2022). "M1 macrophages highly express inducible nitric oxide synthase and secrete IL-1, IL-12, NO, and TNF-α, which have tumor-killing effects." (PMID 35251014, 2022). "Inflammatory cytokines within the tumor microenvironment, such as interleukin (IL)-2, IL-6, IL-10, IFNs and tumor necrosis factor α, have also been shown to induce B7-H4 expression on both tumor cells and monocytes/macrophages." (PMID 34275008, 2022). "In conclusion, we demonstrated that WBP2 drives TNBC migration and invasion under TNF‐α‐induced conditions, which mimic the tumor‐stimulatory microenvironment." (PMID 34197030, 2022). "While associations did not vary by hormone receptor status, except for IL-8, heterogeneity by tumor size was observed for several biomarkers (IL-8, TNF-α, leptin, adiponectin)." (PMID 35948877, 2022). "Muscle waste is driven partly by a procatabolic state invoked by proinflammatory cytokines, such as interleukin-6 and tumor necrosis factor, which are directly released by tumor cells or produced by the host’s immune response." (PMID 36352042, 2022). "While in the chemical carcinogenesis of skin, TNF-α is a promoter for tumor growth, IL-10 produced by B cells facilitates tumor growth in a TNF-α-dependent manner." (PMID 36033455, 2022). "Same group has shown that the mechanisms of muscle depletion is due to increased proteasome- and calpain-dependent proteolysis in tumor bearing rats treated with TNF-alpha synthesis inhibitor, or an antiprotozoal drug blocking the IL-6 and TNF-alpha action." (PMID 35911555, 2022). "NF-kB, indirectly, through TNF-α production which acts as a potent mutagen, contributes to tumor initiation, inducing ROS release and promoting DNA damage, while encoding antiapoptotic regulators, ensuring the survival and proliferation of tumorigenic cells." (PMID 36497384, 2022). "While, the frequency of CD4+IFN-γ+TNF-α− T cells was related to poor prognostic markers as it was higher in patients with larger tumor size and higher stage and showed direct correlation with the number of involved LNs." (PMID 36376825, 2022). "Monocytes from PBMCs were cultured in a medium with GM-CSF, IL4 and TNFα followed by pulsing with tumor cell lysate and treatment with 50% polyethylene glycol." (PMID 36011029, 2022). "Through the secretion of pro-inflammatory cytokines such as IL-6, IL-1β, and TNF-α, macrophages can contribute to tumor-promoting inflammation." (PMID 35565306, 2022). "Like other invariant natural killer T cells, MAIT cells can play a part in antitumor immunosurveillance via producing tumor-killing cytokine like tumor necrosis factor (TNF)-α in the cancer progression." (PMID 35371315, 2022). "Tumor necrosis factor alpha (TNF-α) promotes translocation of nuclear factor kappa-light-chain-enhancer of activated B cells (NFκB) to the nucleus in tumor cells." (PMID 35865547, 2022). "In the context of cancer therapy, pharmacologic targeting of p38 and MK2 was shown to enhance anti-leukemic activity of smac-mimetic by potentiating TNF production, TNF-dependent apoptosis, and tumor cell death." (PMID 36175595, 2022). "IFNγ and TNF cooperate to upregulate the expression of p16Ink4a and p21Cip1 to promote tumor cell senescence through the JAK-STAT1 signaling pathways." (PMID 35409271, 2022). "Tumor necrosis factor (TNF) was identified as a cytotoxic product of immune cells, which is a cancer immunotherapeutic and causes lysis of tumor cells." (PMID 35593465, 2022). "Grouped comparison of paired oxygenation changes in the same tumor revealed that castration-induced hypoxia was TNF dependent." (PMID 36551505, 2022).
tumor (continued). "TNF-α promotes tumor-cell survival via anti-apoptotic intracellular signalling pathways, angiogenesis, and mutagenesis." (PMID 36584036, 2022). "Egg white peptides can stimulate macrophage activity and block the tumor necrosis factor (TNF)-mediated NF-κB pathway, while tumor growth suppressions are linked to ovomucin glycopeptides." (PMID 35757269, 2022). "In sum, the recombinant and TAM-derived TNF-α plays a promotive role in tumor invasion by various signaling pathways." (PMID 35327584, 2022). "Lymphocytes have anti-tumor effects, which can directly kill the tumor cells, but can also inhibit tumor proliferation and migration by secreting a series of cytokines, such as interferon and tumor necrosis factor." (PMID 36005195, 2022). "Macrophage TNFR2 is critical to the antitumor effect of TNF, potentially via increasing nitric-oxide-mediated inhibition effects of tumor angiogenesis." (PMID 35954156, 2022). "Although the pro-inflammatory cytokines TNF, IL-6 and IL-17 contribute to the pathology of tumor-elicited inflammation, these cytokines are crucial for replacing epithelial cells by stimulating the proliferation." (PMID 36611932, 2022). "M1 macrophages release proinflammatory cytokines such as IL-1β, IL-6, and TNF-α to activate innate immunity and kill tumor cells." (PMID 35210436, 2022). "TNF-α was investigated early on as a potential anti-tumor therapy based on its ability to necrotize mouse tumors." (PMID 35574362, 2022). "Cytokines, such as IFN-γ, TNF-α and IL-2, produced by Th1 cells were found to be vital factors in the inhibition of tumor growth." (PMID 35688915, 2022). "Immune cells are the natural source of cytokines; nevertheless, tumor cells are able to produce IL-6 and TNFα as well." (PMID 35269507, 2022). "M1 is characterized by expressing a large amount of inducible nitric oxide synthase and TNF-α, and exert anti-tumor activity by promoting pro-inflammatory and immune responses." (PMID 35237507, 2022). "The anti‐tumor effect represented in the ADP@SWNT/TNFα group was due to the delivery of TNFα via the complex into the tumor." (PMID 34994069, 2022). "More specifically, we have detected increased levels of sICAM-1, CXCL10, CXCL1, CCL5, TIMP-1 and TNFα in tumours treated with VV-αCEA TCE, compared to tumours treated with VV-CTRL or PBS." (PMID 36405739, 2022). "Other reports described tumor vasculature destruction through either high IFN-β-levels injected into the tumor or through STING agonists via TNF-α-production." (PMID 35626062, 2022). "On the other hand, TNFα enhances activation-induced cell death in T cells, that will reduce their viability in the tumor microenvironment." (PMID 35847803, 2022). "The phenotypically immature neutrophils were activated by OrfV and trafficked via the bloodstream to colonize the TME of the lungs, whereby they secreted TNF-α and exhibited enhanced cytotoxic effects against tumor cells." (PMID 36139433, 2022). "Its use in mice caused tumor hyperthermia, PTPN2 depletion, increased T cell infiltration into the tumor, and higher intratumoral IFN-γ and TNF-α levels." (PMID 35911672, 2022). "On the one hand, reactive oxygen species (ROS), hydrogen peroxide, and tumor necrosis factor (TNF) related apoptosis-inducing ligands are released to attack tumor cells." (PMID 36506099, 2022). "Tumor associated Neutrophils (TANs) have been shown to promote B cell chemotaxis to the tumor by secretion of TNFα thereby playing a role in tumor progression." (PMID 35844608, 2022). "As the prime anti-tumor cells, CD8+ T cells can secrete IFN-γ and TNFα to destroy cancerous cells once they contact tumor cells or eliminate tumor cells by releasing perforin and granzyme B through the Fas/FasL pathway." (PMID 36132141, 2022). "Patients in the IRE group had elevated serum levels of immunogenic cytokines, including IL-2, IL-6, and TNF-α, which were related to anti-tumor immunity." (PMID 36428767, 2022).
tumor (continued). "γδT cells can suppress tumors in direct or indirect ways; for instance, IFN-γ and TNF-α, which inhibit tumor growth, are sourced from γδT cells." (PMID 36246403, 2022). "TNF-α is a known tumor motility promoter, correlating with increased metastasis rates in OSCC patients by mediating the expression of TMEM182 and activating the ERK1/2 pathway." (PMID 36143043, 2022). "By increasing the infiltration of CD3+/CD4+ T cells and DX5+ NK cells in the tumor area, the expression of cytokines such as IL-1β, TNF-α, IFN-γ, GM-CSF were increased, and the anti-tumor effect was also observed." (PMID 35757741, 2022). "Activation of the nuclear factor -κB (NF-κB- a transcription factor) pathway in TILs increases the production of TNF-α as well as other proinflammatory cytokines responsible for cell proliferation in tumour cells." (PMID 36420446, 2022). "Mature DCs then secrete numerous pro-inflammatory cytokines, including tumor necrosis factor-α (TNF-α) and interleukin-6 (IL-6), controlling anti-tumor immune responses." (PMID 35692783, 2022). "The underlying mechanism would be the capability of TNF to stimulate activation-induced cell death (AICD) of CD8+ T cells impairing their accumulation in tumors and consequently promoting tumor growth and impeding response to anti-PD-1." (PMID 35847803, 2022). "TNF-α was first discovered by researchers in macrophages, which can induce hemorrhagic necrosis of tumor tissues and thereby inactivate tumor cells." (PMID 35453397, 2022). "In the present study, we used TNF-α to activate SREBP1 in Ca9-22 cells, to mimic the local inflammatory response in the invasive front of cancer, as some tumor cells were reported to produce TNF-α." (PMID 36500345, 2022). "The study found that PD-L1 converts tumor necrosis factor α-induced apoptosis of cancer cells into pyroptosis, resulting in tumor necrosis." (PMID 36090967, 2022). "In line with the observation made by others, our data suggest that IFN-γ and TNF-α impaired the response of the tumor cells to TGF-β." (PMID 35444547, 2022). "TNF-α is a classic inflammatory cytokine hypersecreted during the early stages of tumor growth, and is regarded as a signature product of M1 macrophages." (PMID 36291890, 2022). "TNFα produced in the setting of anti-PD-1 blockage leads to an impairment in the CD8+ tumor infiltrating T lymphocyte responses." (PMID 35847803, 2022). "TNF-α has been shown to counterbalance the Emergence of M2 Tumor Macrophages by promoting M1 polarization." (PMID 35193986, 2022). "Inflammation activates NF-κB through intracellular signaling pathways, induces the cytokines tumor necrosis factor-α (TNF-α) expression of cytokines and can form an inflammatory microenvironment that promotes tumor growth and progression." (PMID 36142321, 2022). "Exosomes from cholangiocarcinoma were found to significantly inhibit NK cells secretion of TNF-α, reducing their anti-tumor function." (PMID 35031075, 2022). "TNF-α is a biologically active polypeptide secreted by macrophages and is the first cytokine used in tumor therapy." (PMID 35783155, 2022). "Lymphocytes are essential to host antitumor immunity through their induction of direct tumor cell cytotoxicity and cytokine secretion, such as tumor necrosis factor alpha and interferon gamma." (PMID 35242712, 2022). "Tumour necrosis factor α (TNF-α), an important cytokine that mediates many inflammatory reactions, is produced by activated macrophages and tumour cells." (PMID 35415239, 2022). "The TNF network acts in a paracrine manner in the tumor microenvironment to affect the angiogenesis and immune cells infiltration." (PMID 36530985, 2022). "Its inhibition of rat glioma tumor-bearing is by enhancing the activity of NK cells and T cells, and increasing the concentration of serum interleukin-2 (IL-2) and TNF-α." (PMID 36686745, 2022).